CAV1 (caveolin 1)
Diseases named in the same sentence as CAV1 in open-access papers (continued):
Sharing a sentence is not in itself a finding about the gene and the disease.
ovarian carcinoma (continued). "In a nutshell, it can be concluded that cisplatin-induced apoptotic ratio is higher in common ovarian cancer compared with ovarian cancer cells with cisplatin-resistance; moreover, it seems that down-regulation of Cav-1 expression by knockdown of Cav-1 can increase cisplatin-induced cell apoptosis." (PMID 31759347, 2019). "In addition, hepatocyte growth factor (HGF) down-regulates E-cadherin, beta-catenin, and caveolin-1, disassembly of cell-cell contacts, and invasion and migration enhancement in human ovarian cancer cells." (PMID 31759347, 2019). "It has also been demonstrated that Cav-1 expression was more membranous in those with ovarian cancer and had short-term survival, which is a similar finding to what we have shown that membranous expression has a positive correlation with grade, and this factor is associated with poorer survival." (PMID 22353809, 2012). "Additionally, CAV1 can be found in the nucleus of ovarian cancer cells, suggesting that CAV1 may also inhibit in ovarian cancer." (PMID 37124501, 2023). "This aspect could represent an advantage for the application of CD-NSs, since CAV-1 is down-regulated in the vast majority of ovarian carcinomas 60, and its expression greatly change in different type of cancers, depending on tumor staging and the tumor microenvironment." (PMID 33564618, 2021). "Plasma exosomal CAV1 may be a potential biomarker for the prognosis in ovarian cancer patients." (PMID 34234869, 2021). "Additionally, Cav-1 could promote the chemoresistance of ovarian cancer by targeting apoptosis through the Notch1/Akt/NF-κB pathway." (PMID 27184229, 2016). "In a concurrent study of six CAF markers, viz., α-SMA, FAP, FSP-1, CD29, PDGFR-β, and CAV-1 (caveolin-1), four distinct CAF subpopulations, viz., CAF-S1, S2, S3, and S4, were found in human breast and ovarian cancers with distinct expression profiles." (PMID 40805183, 2025). "Ovarian cancer cells (OV-90, TOV-21G, and Caov-3) were tested and showed a significant reduction in caveolin-1 protein content." (PMID 38255998, 2024). "We also found that apoptosis-related genes, URI1, PAK2, PARP1, CLU and TIMP3, were highly expressed, while immune-related genes, UBB, RPL11, CAV1, NUPR1 and Hsp90ab1, were lowly expressed in ovarian cancer cells." (PMID 37124501, 2023). "RT-qPCR analysis revealed that URI1, PAK2, PARP1, CLU, and TIMP3 were significantly upregulated, while UBB, RPL11, CAV1, NUPR1, and Hsp90ab1 were significantly downregulated in the ovarian cancer samples." (PMID 37124501, 2023). "For OS prediction in ovarian cancer patients, the AUROC of plasma exosomal CAV1 was 0.78 (95% CI: 0.70-0.84)." (PMID 34234869, 2021). "For OS prediction in ovarian cancer patients, the AUROC of plasma exosomal CAV1 was 0.78 (95% CI: 0.70-0.84), with a sensitivity 65.1 (95% CI: 49.1-79.0) and a specificity 81.2 (95% CI: 72.8-88.0)." (PMID 34234869, 2021). "Low exosomal CAV1 levels were closely related to the FIGO stages I/II, low grade, lymph node metastasis and prognosis of ovarian cancer patients." (PMID 34234869, 2021). "Kaplan-Meier method was used to explore the relationship between plasma exosomal CAV1 levels and OS or DFS in ovarian cancer patients." (PMID 34234869, 2021). "Among all ovarian cancer patients, DFS was worse in patients who had low plasma exosomal CAV1 levels compared with that in patients with high plasma exosomal CAV1 levels (P < 0.001)." (PMID 34234869, 2021). "Plasma exosomal CAV1 levels has a better performance for OS and DFS prediction in ovarian cancer patients than CAV1 protein and/or mRNA and is a useful prognostic biomarker 14,34." (PMID 34234869, 2021). "The AUROC of plasma exosomal CAV1 were 0.76 (95% CI: 0.68-0.82) and 0.78 (95% CI: 0.70-0.84) for DFS and OS prediction in ovarian cancer patients, respectively." (PMID 34234869, 2021).
ovarian carcinoma (continued). "Among all ovarian cancer patients, DFS was worse in patients who had low plasma exosomal CAV1 levels compared with patients with high plasma exosomal CAV1 levels." (PMID 34234869, 2021). "Clinicopathologic features and distribution of CAV1 and ATG4C in the stroma of 79 epithelial ovarian cancer patients." (PMID 32401768, 2020). "Clinicopathologic features and distribution of CAV1 and ATG4C in cancer cells of 95 epithelial ovarian cancer patients." (PMID 32401768, 2020). "Our data also showed that ZEB1, Snail, and Caveolin-1 are regulated by CD44, indicating the crucial role of CD44 in the initiation of EMT in ovarian cancer." (PMID 31497537, 2019). "The re-expression of Cav-1 in OVCAR-3, an ovarian carcinoma cell line, prevents tumor cell survival in vitro." (PMID 31759347, 2019). "In ovarian cancer, four subtypes of CAF populations (CAF-S1 to CAF-S4) have been discovered by analyzing CAF markers of FAP, α-SMA, CD29, PDGFRβ, FSP1, and caveolin 1 (CAV1)." (PMID 35681617, 2022). "The levels of exosomal CAV1 in patient plasma were significantly higher in ovarian cancer patients with no lymph node metastasis than in those with lymph node metastasis." (PMID 34234869, 2021). "The levels of exosomal CAV1 in patient plasma were significantly higher in ovarian cancer patients with no lymph node metastasis than those with lymph node metastasis (P < 0.01)." (PMID 34234869, 2021). "Research in the ovarian cancer TME has identified at least four different CAF subpopulations that express distinct molecular signatures characterized by variable expression of CD29, CD10, FAP, α-SMA, FSP1, PDGFR-β, podoplanin, and caveolin-1." (PMID 34201616, 2021). "In ABCB1 deficient taxol-resistant A549 cancer cells, Cav-1 upregulation was observed and Cav-1 overexpression correlated with little ABCB1 protein expression in human ovarian cancer cells, and ABCB1 overexpression was not localized in caveolae." (PMID 26431273, 2015). "Interestingly, a study comparing disease-free intervals in ovarian cancer patients reported a negative correlation with cav-1 exosomes, revealing a paradoxical relationship between exosome expression and cancer prognosis." (PMID 38067397, 2023). "In the areas of breast and ovarian cancer, CAF subtypes have been defined based on multicolor flow cytometry yielding the four subtypes depending on how they stained for the fibroblast markers FAP, CD29, αSMA, S100-A4, PDGFRβ, and CAV1, accumulating differently in different tumors." (PMID 37745296, 2023). "Finally, we did not explore the mechanism of action of exosomes and CAV1 in occurrence, development and therapy of ovarian cancer." (PMID 34234869, 2021). "Second, this study did not evaluate plasma exosomal CAV1 levels in the diagnosis of ovarian cancer." (PMID 34234869, 2021). "However, the clinical significance of CAV1 and ATG4C expression in epithelial ovarian cancer (EOC) remains largely unknown." (PMID 32401768, 2020). "Interestingly, the neo-expression of E-cadherin in previous E-cadherin down-regulated ovarian carcinoma did not inhibit the release and migration of cells from the primary tumor because the expression of Cav-1 was down-regulated even though E-cadherin level was adequate." (PMID 31759347, 2019).
hepatocellular carcinoma (67 papers, 2006 to 2025). A malignant tumor that arises from hepatocytes. "For example, in hepatoma cells, increased cav-1 expression induced by plasmalogens was associated with decreased Akt activity, suggesting inhibitory effects of cav-1 on PI3K." (PMID 30995923, 2019). "Taken together, the results indicate that swine liver-derived natural ChoPlas inhibits hepatoma cell proliferation associated with Caveolin-1 and PI3K/Akt signals." (PMID 24143228, 2013). "Further, 5-AZA treatment causes up-regulated CAV1 expression in hepatoma cells." (PMID 26112043, 2015). "Indeed, in a caveolin-1 (cav-1)-deficient cell line (human hepatoma 7) and embryonic fibroblasts from a cav-1 knockout mouse, SV40 exploits an alternative, cav-1-independent pathway and this alternative pathway is also available in wild-type embryonic fibroblasts." (PMID 16603059, 2006). "In this context, a study demonstrated that Caveolin-1 (CAV1) upregulates POFUT1 expression in hepatocellular carcinoma by activating the MAPK signaling pathway." (PMID 40773107, 2025). "Overexpression of caveolin-1 can increase the proliferation and ensure the survival of the hepatoma cells in vitro." (PMID 38338453, 2024). "ACADM, an enzyme that catalyzes the first step of mitochondrial fatty acid-oxidation pathway, has been shown to inhibit the progression of hepatocellular carcinoma via regulation of CAV1 and SREBP121." (PMID 37460577, 2023). "RUNX2 expression appeared to be repressed by caveolin-1, a major structural protein of caveolae; the RUNX2-induced transcription of miR24 was attenuated during caveolin-1-mediated cell invasion in hepatocellular carcinoma." (PMID 37108164, 2023). "Cav1 is involved in hepatocellular carcinoma and hepatocellular differentiation through its activation of MAPK signaling, and inhibition of Cav1 is associated with the anti-inflammatory effects of some drugs." (PMID 37817228, 2023). "Different patterns of CAV-1 expression in hepatocellular carcinoma suggest that this molecule plays an important role in tumor progression too." (PMID 36556936, 2022). "We have demonstratedthat the upregulation of caveolin-1, a key element in the regulationof membrane tension, is relevant in cirrhosis and hepatocellular carcinoma,and can be recapitulated in fibrosis-mimicking 3D constructs." (PMID 35255206, 2022). "At the stage conducted on hepatocellular cancer stem cell lines, it was shown that miR-124, whose expression level was high, suppressed the activity of the CAV1 (Caveolin-1) gene found using bioinformatic screening." (PMID 36362406, 2022). "We then show that TIMP-1 and caveolin-1 expression increasesin cirrhosis and hepatocellular carcinoma." (PMID 35255206, 2022). "In hepatocellular carcinoma, CAV1 is over-expressed and promotes cell motility and invasion by inducing EMT." (PMID 31362353, 2019). "The pro-metastatic capacity of Cav1 is mediated by the S100 calcium-binding protein P and is stimulated by hypoxic conditions, which increase Cav1 expression in hepatocellular carcinoma." (PMID 28913175, 2017). "CAV1 promotes hepatocellular carcinoma cell progression and metastasis through the Wnt/β-catenin pathway, whereas it suppresses focal adhesion turnover and migration of metastatic cells." (PMID 28099944, 2017). "With using proteomic identification, Cav-1 was found to be elevated in metastatic hepatocellular cancer cell lines." (PMID 26431273, 2015). "In hepatocellular carcinoma, Cav-1 expression was also markedly upregulated in specimens or cell lines, and Cav-1 upregulation positively correlated with histological differentiation, venous invasion, intrahepatic metastasis and VEGF expression." (PMID 26431273, 2015). "Caveolin-1 (Cav-1) has been recently identified to be over-expressed in hepatocellular carcinoma (HCC) and promote HCC cell motility and invasion ability via inducing epithelial-mesenchymal transition (EMT)." (PMID 24454730, 2014).
hepatocellular carcinoma (continued). "Our data suggests that ChoPlas-induced caveolin-1 over-expression down-regulates PI3K/Akt phosphorylation downstream of Akt in hepatoma CBRH7919 cells." (PMID 24143228, 2013). "Our previous studies showed that Cav-1, as a tumor regulator, is involved in cell proliferation, transformation and apoptosis of breast cancer and hepatoma." (PMID 24143228, 2013). "Although caveolin-1 expression is elevated in hepatocellular carcinoma (HCC), its function as a tumor suppressor or promoter is still debated." (PMID 23339737, 2013). "In hepatocellular carcinoma, Cav1 up-regulation seems to promote cell proliferation, migration and invasion in vitro and metastatic potential in vivo.." (PMID 23521716, 2013). "In the present study, it was shown that exogenous natural ChoPlas treatment activated Caveolin-1 expression in hepatoma CBRH7919 cells, indicating that exogenous ChoPlas-induced cell proliferation inhibition is dependent on caveolin-1 over-expression." (PMID 24143228, 2013). "The DNA methylation status of the caveolin-1 promoter was examined by nested methylation-specific PCR of 33 hepatitis B virus (HBV)-infected hepatocellular carcinoma (HCC) samples." (PMID 22894556, 2012). "Caveolin-1 was significantly decreased at both mRNA and protein levels after Hbx transfection, indicating that HBx downregulated caveolin-1 expression in SMMC-7721 hepatoma cells." (PMID 22894556, 2012). "Independently, using freeze-fracture immunoelectron microscopy, Fujimoto and colleagues have shown that coexpression of Cav-1 and Cav-2 resulted in a more efficient formation of deep caveolae than Cav-1 alone in hepatocellular carcinoma cell line (HepG2)." (PMID 22229094, 2011). "In support of this idea, we recently found that CHIKV productively infects the human hepatoma HuH7 cell line devoid of cav-1 required for caveolar vesicles formation." (PMID 20628602, 2010). "The expression level of Cav-1 is positively correlated with the invasiveness of hepatocellular carcinoma (HCC), and knocking out Cav-1 can inhibit the epithelial mesenchymal transition (EMT) process through Wnt/β-catenin pathway, thereby inhibiting the malignant behavior of HCC metastasis." (PMID 41030451, 2025). "Meanwhile, the expression of TIMP1 and CAV1 increases in cirrhosis and hepatocellular carcinoma." (PMID 36146640, 2022). "Hongxiu Yu reported that CAV1 could promote the EMT process via the Wnt/β-catenin pathway in hepatocellular carcinoma." (PMID 36147736, 2022). "In addition, in hepatocellular cancer cell lines, CAV1 is required for the induction of survival via the TGF-β/EGFR/pAkt signaling pathway." (PMID 32458269, 2020). "Thus, CAV1 is considered a marker of poor prognosis in hepatocellular carcinoma patients who had undergone tumor resection." (PMID 32458269, 2020). "Knockdown of Cav1 reduces e.g. IGF1 signaling in H9C2 rat cardiomyoblasts whereas Cav1 overexpression significantly increases IGF1-induced internalization of IGF-1R in human hepatocellular carcinoma cells." (PMID 32458278, 2020). "Tumoral Cav-1 expression increased in cancers cells compared to their normal counterparts, whereas stromal Cav-1 expression decreased in cancer tissues compared to adjacent normal tissues, such as pancreatic cancer, esophageal cancer, and hepatocellular carcinomas." (PMID 28828003, 2017). "Notably, our group reported that caveolin-1 appeared to regulate the localization and cellular activity of GnT-III in hepatoma cells, leading to the possibility of bisecting GlcNAc being involved in caveolin-1-related cancer phenotypes." (PMID 27136596, 2016). "However, these latest studies were all undertaken using only immunohistochemical evaluation, and in most cases, caveolin-1 overexpression was recorded in the cytoplasm of liver carcinoma cells." (PMID 25243186, 2014).
hepatocellular carcinoma (continued). "Similarly, elevated levels of Cav1 increased cell motility and invasion in the human hepatocellular carcinoma cell lines (HepG2 and Huh7), and caveolae disruption reduced SNU-449 and SNU-47 cell motility and invasion." (PMID 23521716, 2013). "A simian virus 40 activated endocytic pathway in human hepatoma 7 (deficient in cav-1) and embryonic fibroblasts from cav-1 null mice was described that did not involve either clathrin-coated pit or caveolae." (PMID 24312378, 2013). "Studies on hepatocellular carcinoma (HCC) suggest that Cav-1 can inhibit autophagy, promote proliferation, migration and angiogenesis of cancer cells." (PMID 41030451, 2025). "Caveolin-1 (Cav-1), an essential protein found in a structural pit, acts as an oncogene in hepatocellular carcinoma (HCC) by contributing to abnormal glycosylation of proteins." (PMID 39228402, 2024). "Recently, several studies have demonstrated that caveolin-1 overexpression is involved in apoptosis resistance, angiogenesis, and invasiveness in hepatocellular carcinoma (HCC)." (PMID 32676485, 2020). "In relation to autophagy, CAV1 appears to have an inhibitory role in hepatocellular carcinoma (HCC) since autophagy markers such as ATG5, Beclin-1, and LC3II were upregulated in HCCLM3-shCAV1 cells compared to mock cells." (PMID 31362353, 2019). "Promoter hypermethylation of CAV1 is also seen in hepatocellular carcinoma (HCC) cell lines and HCC tissues and is accompanied by reduced expression of CAV1." (PMID 26112043, 2015). "There is little information concerning CAV1 expression and role in hepatocellular carcinoma (HCC) progresion and metastasis." (PMID 25180681, 2014). "We analyzed the expression of Caveolin-1 in 96 hepatocellular carcinoma (HCC), 29 cirrhosis, 20 normal liver tissues and 9 HCC cell lines by immunostaining and western blotting, respectively." (PMID 19239691, 2009). "In hepatocellular carcinoma (HCC), TEVs enriched with Cav1 and Cav2 have been shown to induce migration and invasion in non-motile hepatocytes." (PMID 40963741, 2025). "A previous study reported that CAV-1 is involved in EMT regulation in non-small cell lung cancer and hepatocellular carcinoma." (PMID 38298655, 2024). "In caveolin-1-dependent hepatocellular carcinoma invasion, RUNX2 expression appeared to be suppressed by caveolin-1 along with the repression of RUNX2-induced miR24 transcription." (PMID 37108164, 2023). "In hepatocellular carcinoma and renal cell carcinoma, Cav-1 is induced by hypoxia via hypoxia-inducible factor 1α (HIF-1α), suggesting a possible role of Cav-1 in tumor angiogenesis." (PMID 34287575, 2021). "Cav-1 expression has previously been reported to lead to activation of MMP2 and MMP9 promoting invasion in hepatocellular carcinoma cell lines and non-small lung carcinoma." (PMID 34490102, 2021). "In addition, Cav-1 was reported to be involved in the anti-cancer activity of Res in a human hepatocellular carcinoma (HCC) model, while limited data existed regarding the modulation of Res on endothelial permeability through Cav-1 in vitro and in vivo." (PMID 25419974, 2014). "In this study, we observed that Caveolin-1(CAV1) expression can increase the cytotoxic and pro-apoptotic activity of RES in a dose- and time-dependent manner both in vitro and in vivo in a Hepatocellular Carcinoma animal model." (PMID 19321006, 2009). "In hepatocellular carcinoma, anoikis resistance of hepatoma cells has been determined to require PAK1 activity, and CAV1 could also confer resistance of hepatoma cells to anoikis by activating the IGF‐1 pathway." (PMID 36507553, 2023). "This is further supported by studies demonstrating a lack of association between sex and the expression of CAV-1 and MMP-1 in patients with CHC or CHC-related complications, such as hepatocellular carcinoma." (PMID 36556936, 2022).